SSTR2 (somatostatin receptor 2)
Diseases named in the same sentence as SSTR2 in open-access papers (continued):
Sharing a sentence is not in itself a finding about the gene and the disease.
prostate carcinoma (continued). "In addition, the chromatin modulators, including demethylating agents and HDAC inhibitors, were reported to upregulate SSTR2 expression and thus increased tumor uptake of the radiolabeled octreotide in neuroendocrine and prostate cancer cells." (PMID 36732057, 2023). "Only prostate cancer and renal cancer SSTR2 IHC rates were below 25%." (PMID 35264912, 2022). "The lowest positive SSTR2 IHC rate was found in prostate cancer (16.7%)." (PMID 35264912, 2022). "Lower mRNA levels of SSTR2 were expressed in the metastases from prostate cancers than in primary prostate cancers, meanwhile, decreased SSTR2 could predict poor prognosis of prostate cancer." (PMID 26796520, 2016). "SSTR2, a G-protein coupled receptor for somatostatin is an inhibitory hormone produced by immune and neuroendocrine cells It is also expressed in several types of cancers, including prostate cancer and leukemia." (PMID 26461935, 2015). "In conclusion, most prostate cancers are indeed SSTR2-negative and loss of SSTR2 strongly predicts an unfavorable tumor phenotype and poor prognosis." (PMID 25010045, 2014). "Human prostate biopsies and studies of SHP-1 or SSTR2 expression in prostate carcinoma are limited." (PMID 19365586, 2009). "SSTR2 is preferably expressed in the normal prostate, while SSTR1 and SSTR5 are expressed in prostate cancer." (PMID 33586406, 2021). "To test if the changes in SSTR2 expression detected by IHC could be confirmed on the transcriptional level, we performed in silico expression analysis utilizing two publicly available GEO datasets of human prostate cancer gene expression arrays (GDS2545 and GDS4109)." (PMID 25010045, 2014). "The aim of this study is evaluate the expression of both SSTR2 and SHP-1 (PTPN6) in normal prostate and their variation through tumoral progression in human prostate cancer (different Gleason scores)." (PMID 19365586, 2009). "The comparison of normal and cancerous prostate epithelium in the present study by IHC demonstrated that SSTR2 is not overexpressed, but instead generally downregulated in prostate cancers." (PMID 25010045, 2014). "While membranous SSTR2 staining was always seen in normal prostate epithelium, SSTR2 staining was absent in more than half (56.1%) of 2,195 interpretable prostate cancer samples." (PMID 25010045, 2014). "SSTR2 expression as determined by IHC was absent in 1,231 (56.1%) of interpretable prostate cancer samples." (PMID 25010045, 2014). "In silico analysis confirmed lower SSTR2 gene expression in prostate cancers vs. normal adjacent tissue (p = 0.0424), prostate cancer metastases vs. primary cancers (p = 0.0011) and recurrent vs. non-recurrent prostate cancers (p = 0.0438)." (PMID 25010045, 2014). "Indeed, most prostate cancers are SSTR2 negative and SSTR2 expression seems to be an important factor in the pathogenesis of prostate cancer." (PMID 25010045, 2014). "Other groups found diminished or absent SSTR2 expression in prostate cancers." (PMID 25010045, 2014). "Ki67 LI increased with decreasing SSTR2 IHC intensity in prostate cancer cells from 2.8±0.4 (strong SSTR2 IHC) over 3.8±0.4 (intermediate SSTR2 IHC) and 5.0±0.2 (weak SSTR2 IHC) to 5.9±0.2 in SSTR2-negative prostate cancers (arithmetical mean ± standard error of the mean, p<0.0001)." (PMID 25010045, 2014). "Therefore, SSTR2 expression seems an important factor in the pathogenesis of prostate cancer and re-introduction of the receptor in SSTR2-negative prostate cancers may feature a promising target for novel gene therapy approaches." (PMID 25010045, 2014).
neuroblastoma (15 papers, 1999 to 2025). Neuroblastoma (NB) is the most common solid, extracranial childhood tumor. "SSTR2 expression has also been associated with favourable outcome in patients with pancreatic NETs and childhood neuroblastomas." (PMID 28467778, 2017). "In this study, mutation screening of the SSTR2 gene in 43 neuroblastoma tumours was carried out with polymerase chain reaction-based single-stranded conformation polymorphism/heteroduplex (SSCP/HD) and DNA sequencing, and none of the tumours showed any aberrations in the SSTR2 gene." (PMID 10604740, 1999). "Pediatric malignancies, such as neuroblastoma, pheochromocytoma, and paraganglioma, have been shown to express SSTR2, and 68Ga-DOTA-TATE is currently being used to evaluate these pediatric neoplasms." (PMID 40106206, 2025). "Pediatric malignancies, such as neuroblastoma, pheochromocytoma, and paraganglioma, are known to express SSTR2 and 68Ga-DOTA-TATE is currently being used to evaluate these pediatric neoplasms." (PMID 40106206, 2025). "Between 75 and 90% of all clinical samples of neuroblastoma are considered positive for SSTR2 expression, and multiple early phase clinical trials have already shown promising results using [177Lu]Lu-DOTATATE for treatment of neuroblastoma." (PMID 37823909, 2024). "This study demonstrates the potential for a theranostic approach using [64/67Cu]Cu-SARTATE for the detection and treatment of SSTR2-positive neuroblastoma MRD." (PMID 33630166, 2021). "Several studies have studied SSTR expression in neuroblastoma, and the number of SSTR2 (to which of the five receptors 177Lu-DOTATATE has the highest affinity) positive neuroblastoma tumors is reported to range from 75 to 90%." (PMID 34827693, 2021). "In this study, we successfully imaged 68Ga-DOTA-TATE uptake in SSTR2-positive neuroblastoma xenografts with micro-PET/CT." (PMID 29097943, 2017). "Expression of the somatostatin receptor 2 (SSTR2), localized in chromosome region 17q24, has in previous studies been shown to be positively related to survival in neuroblastoma." (PMID 10604740, 1999). "High SSTR2 expression is mainly seen in more differentiated neuroblastoma." (PMID 33916640, 2021). "Furthermore, SSTR2 was expressed in all surgical neuroblastoma specimens we analyzed by immunohistochemistry." (PMID 33990938, 2021). "In contrast, SSTRs, especially SSTR2, have been shown to be highly expressed in various human tumors including pancreatic, small cell lung, and carcinoid tumors, as well as paraganglioma, pheochromocytoma, and neuroblastoma." (PMID 29097943, 2017). "The purpose of this study was to evaluate the correlation of somatostatin receptor-2 (SSTR2) expression with 68Ga-DOTA-TATE uptake and 177Lu-DOTA-TATE therapy in neuroblastoma (NB) xenograft models." (PMID 29097943, 2017). "In some cell lines, two bands were detected using the monoclonal SSTR2 antibody (ab134152, Abcam), which is consistent with a previous report in which two bands were also detected in IMR-32 neuroblastoma cell lysates." (PMID 29097943, 2017). "Furthermore, overexpression of SSTR2, one of the receptor targets for 177Lu-DOTATATE, is found in 75–90 % of all neuroblastoma cases." (PMID 34827693, 2021). "A similar approach may be beneficial for the imaging and treatment of SSTR2-positive NB, and [68Ga]Ga-DOTA-TATE for PET imaging of SSTR2-positive neuroblastoma followed by treatment with either 177Lu- or 90Y-labeled DOTA-TATE has shown promising initial results." (PMID 33630166, 2021).
neuroblastoma (continued). "However, a direct comparison of [67Cu]Cu-SARTATE and [131I]mIBG would be inherently complex, as it is known that expression of SSTR2 and the noradrenaline transporter (NAT) on neuroblastoma tumors does not overlap, which would introduce a confounding variable." (PMID 33630166, 2021).
lung carcinoma (14 papers, 2013 to 2024). "Also, studies indicate that SSTR2-mediated signalling is involved in tumour growth and lung cancer survival, which was further linked to highly active metabolism and loss of apoptotic signalling due to lack of P38 and Rb in SCLC." (PMID 38203605, 2023). "All five receptor subtypes are present in lung cancer and exert a significant role; however, SSTR2 is the prominent receptor subtype with critical pathological significance in lung cancer." (PMID 38203605, 2023). "SSTR2 are highly overexpressed in many forms of lung cancers that are difficult to be diagnosed at early stages." (PMID 34138386, 2021). "In this proof-of-principle study, xenografts of lung cancer H69 cells served as a SSTR2-positive tumor model." (PMID 33768405, 2021). "OCT with its specificity to bind to SSTR2 on the surface of lung cancer cells, we achieved the goal of recognizing lung cancer cells by identification and imaging of miR-155 at both cellular and animal levels." (PMID 30621480, 2018). "The octreotide-conjugated chitosan-molecular beacon nanoparticles (CS-MB-OCT) can specifically bind to SSTR2 expressed by the lung cancer cells to achieve the goal of identification of lung cancer cells and imaging miR-155 in vivo and in vitro." (PMID 30621480, 2018). "Here, we evaluated somatostatin receptor 2 targeting and nucleolin targeting for therapeutic delivery to cancer stem cells from lung cancer." (PMID 28542563, 2017). "Furthermore, studies have also shown the use of SSTR2 and dopamine receptor 2 in combination with mTOR inhibitor in lung cancer cells NCI-H727." (PMID 38203605, 2023). "Study has shown that SSTR2 can inhibit cell proliferation by upregulating p21 and p16 or increasing caspase-3 and decreasing PARP expression in human pancreatic and lung cancer cell lines." (PMID 33318294, 2020).
pheochromocytoma (14 papers, 2014 to 2026). "Consequently, this study evaluates the pharmacokinetic effects of the albumin-binding domain cLAB4 on theranostic performance of copper‐67-labeled NODAGA-TATE variants in an SSTR2-positive mouse pheochromocytoma (MPC) model." (PMID 39310112, 2024). "This preclinical study, conducted in an SSTR2-positive mouse pheochromocytoma model, demonstrates efficacy of targeted somatostatin receptor radionuclide therapies with [67Cu]Cu‐NODAGA-TATE and [67Cu]Cu‐NODAGA-cLAB4‐TATE." (PMID 39310112, 2024). "68Ga-SST targeting somatostatin receptor 2 (SSTR2) shows promising results for the detection of pheochromocytoma and paraganglioma." (PMID 35158836, 2022). "A high percentage of patients with metastatic paraganglioma and pheochromocytoma express somatostatin receptors, especially SSTR2, which can be used for PRRT." (PMID 32664679, 2020). "Investigations in SSTR2-positive pheochromocytoma allograft mice demonstrated that the albumin-binding [64Cu]Cu‐NODAGA-cLAB4‐TATE has favorable pharmacokinetic properties resulting in increased uptake and retention in tumors compared to its non-albumin-binding counterpart." (PMID 39310112, 2024). "One previous report on the effects of reactivated EPAS1 expression in mouse pheochromocytoma cells in vitro provides evidence that HIF-2α downstream signaling may be involved in SSTR2 downregulation." (PMID 36946182, 2023). "Furthermore, a recent animal study showed that SSTR2 levels can be stimulated in mouse pheochromocytoma allografts via treatment with epigenetic drugs." (PMID 36946182, 2023). "Results revealed that pheochromocytomas and paragangliomas similarly display a predominant SSTR2 and SSTR1 expression regardless of molecular cluster." (PMID 41928014, 2026).
metastatic disease (13 papers, 2014 to 2025). "In a multivariate analysis, SSTR2 IHC positivity was significantly associated with metastatic disease (P < .001), independently of germline SDHB mutations or tumor size." (PMID 36946182, 2023). "As previous research on DNA methylation in lung NET lacked detailed clinical characterization, we wanted to assess the DNA methylation profiles of known prognostic subgroups, i.e., histologic subtype, metastatic disease, SSTR2 status, and endocrine activity." (PMID 40072638, 2025). "The authors reported an association of SSTR2 expression with SDHB/SDHx mutations and metastatic disease, and confirmed a high disease control rate of somatostatin receptor-based therapies in metastatic PPGLs." (PMID 40149362, 2025). "When metastatic disease occurs, SSTR2 expression can be used a possible target for somatostatin analogues." (PMID 38374188, 2024). "Targeting the GRPR and SSTR2 for nuclear imaging and/or treatment has the potential to improve BC care in primary as well as metastatic disease." (PMID 28107508, 2017). "Our data show, that SSTR2 downregulation is strongly linked to unfavorable tumor phenotype, early PSA relapse and onset of metastatic disease." (PMID 25010045, 2014). "In cases of metastatic disease, SSTR2 expression may serve as a potential target for somatostatin analog therapy." (PMID 40538845, 2025). "SSTR2 IHC scoring of the primary tumor and metastatic tumor lesions." (PMID 39324010, 2024). "SSTR2 expression was independently associated with SDHB/SDHx mutations and metastatic disease." (PMID 36946182, 2023). "Moreover, SSTR2 expression was significantly associated with metastatic disease independent of SDHB/SDHx mutation status (P < .001)." (PMID 36946182, 2023). "Moreover, SSTR2 expression is associated with metastatic disease independent of SDHB/SDHx mutation status." (PMID 36946182, 2023). "In order to validate the findings of previous studies we performed immunohistochemical staining of SSTR2 on 402 NPC primary, recurrent and metastatic tumor samples (detailed in Methods) from European and Asian centers as well as one US center." (PMID 33402692, 2021). "The presented data indicates that nuclear based imaging and therapy has the potential to improve BC patient care in primary as well as in metastatic disease, by targeting GRPR and SSTR2." (PMID 28107508, 2017). "SSTR2 and norepinephrine transporter overexpression plays a crucial role in the uptake of radiolabeled SSAs (177Lu or 90Y-SSAs) and of 131I-MIBG, which makes them a target for the therapy of metastatic tumors." (PMID 40149362, 2025).
pancreatic neuroendocrine tumor (13 papers, 2016 to 2026). Pancreatic endocrine tumor, also known as pancreatic neuroendocrine tumor (PNET), describes a group of endocrine tumors originating in the pancreas that are usually indolent and benign, but may have the potential to be malignant. "The SSTR2 status in NET tumor cells evaluated by immunohistochemistry has been reported to be associated with the therapeutic efficacy of SSAs in pancreatic NETs (PanNETs) and acromegaly." (PMID 35159042, 2022). "Pancreatic neuroendocrine tumors (pNETs) often overexpress somatostatin receptor type 2 (SSTR2), making them ideal targets for theranostics, which integrates molecular imaging with targeted radionuclide therapy." (PMID 40389624, 2025). "Pancreatic neuroendocrine tumors (PNET) express high levels of somatostatin receptor type 2 (SSTR2), a unique target for both tumor imaging and therapy." (PMID 37487000, 2023). "Somatostatin receptor 2 (SSTR2) immunoreactivity serves as a predictive marker of the therapeutic efficacy of SSAs in pancreatic NETs." (PMID 35159042, 2022). "For example, octreotide (OCT), a synthetic analog of somatostatin, was exposed on AAVP for the delivery of tumor necrosis factor (TNF) to somatostatin receptor type-2 (SSTR-2) expressing pancreatic neuroendocrine tumors." (PMID 33671476, 2021). "There have been a few studies of SSTR2 expression and compared their clinicopathologic correlation, including patients’ survival in the pancreatic NETs, but no previous large cohort studies in rectal NETs." (PMID 38374188, 2024). "Case report: We presented the case of 59-year-old patient, diagnosed with non-functional well-differentiated pancreatic neuroendocrine tumor grade II (NET G2) with the presence of chromogranin A, synaptophysin and somatostatin receptor 2, together with liver and bone metastases." (PMID 27928440, 2016).
somatotropinomas (13 papers, 2013 to 2025). "AIP-mutated somatotropinomas have been reported to have lower somatostatin receptor type 2 (SSTR2) expression and therefore lower response to first generations of somatostatin analogues." (PMID 33805450, 2021). "In somatotropinomas, a higher expression of the SSTR2 gene was associated with higher efficacy of octreotide compared with pasireotide, whereas tumors with a higher level of SSTR5 tended to respond better to pasireotide." (PMID 34205778, 2021). "Somatostatin receptor subtype 5 mRNA was highest in somatotropinomas, followed by SSTR2 > SSTR3 >> SSTR1 >>> SSTR4." (PMID 39202532, 2024). "Two other researchers’ groups found that in somatotropinomas and normal pituitary glands, the mRNA transcripts and proteins of SSTR2 and SSTR5 were expressed in all samples." (PMID 39202532, 2024). "E-cadherin and SSTR2 immunostaining in somatotropinoma tissue were investigated in 24/47 and 18/47 patients, respectively." (PMID 38027102, 2023). "Wildemberg showed that low SSTR2 expression can predict the failure of somatotropinomas to respond biochemically to SST analog treatment." (PMID 37900156, 2023). "SSTR5 is also expressed in abundance on somatotropinomas, providing rationale for the use of pasireotide in patients uncontrolled on SSTR2-preferential first-generation somatostatin analogues." (PMID 32217809, 2020). "In conclusion, the systematic evaluation of DRD and SSTR expression in somatotropinomas has revealed an association between the response to SSAs treatment and DRD4, DRD5, SSTR1 and SSTR2 expression." (PMID 29266696, 2018). "In conclusion, we found that ZAC1 and SSTR2 expression levels are reduced in NFPA compared to somatotropinomas and normal pituitaries." (PMID 24098585, 2013). "On the other hand, SSTR2 was lower in the NFPA than in the somatotropinomas and normal pituitaries (p values of 0.001 and 0.01, respectively)." (PMID 24098585, 2013). "In somatotropinomas and normal pituitaries, the SSTR2 and 5 mRNA transcripts and proteins were expressed in all of the samples." (PMID 24098585, 2013). "The ZAC1 mRNA expression was significantly lower in NFPA than in somatotropinomas and in normal pituitaries (p<0.001 for both), as well as the SSTR2 (p=0.001 and 0.01, respectively)." (PMID 24098585, 2013). "While somatotropinomas primarily express both SSTR2 and SSTR5, which mediate their response to first-generation somatostatin analogs or Pasiroetide, the expression profile in corticotroph tumors is more heterogeneous and involves a predominant expression of SSTR5." (PMID 40364036, 2025). "In somatotropinomas, SSTR5 was the predominant SSTR subtype detected, followed by SSTR2, SSTR3 and SSTR1." (PMID 29266696, 2018). "In somatotropinomas, the expression levels of SSTR5 were positively correlated with SSTR2 (r = 0.49, Spearman FDR adjusted P < 0.0001) and SSTR3 (r = 0.28, P = 0.03)." (PMID 29266696, 2018). "Tumor shrinkage has been observed in approximately 40% of somatotropinomas and in 11–13% of NFPA after treatment with octreotide and lanreotide, which bind preferentially to SSTR2." (PMID 24098585, 2013). "In respect to the SSTR, lower SSTR2 and higher SSTR3 mRNA expression levels were found in the NFPA compared with both the normal pituitaries and the somatotropinomas." (PMID 24098585, 2013). "This could be related to the lower SSTR2 expression at baseline in somatotropinomas resistant to SSAs, or because of feedback mechanisms of the GH–IGF-I axis and the downregulation of SSTR2 due to prior SSA treatment." (PMID 32121432, 2020). "However, the low expression levels of ZAC1 and SSTR2 may be involved in the resistance to somatostatin analogs that is observed in these tumors, partially justifying the failure of tumor shrinkage that is observed in NFPA compared to somatotropinomas." (PMID 24098585, 2013).